IFNG (interferon gamma)
Diseases named in the same sentence as IFNG in open-access papers (continued):
Sharing a sentence is not in itself a finding about the gene and the disease.
cervical tumors (9 papers, 2009 to 2025). "Also, we compared the relationships between IDO1 and IFNG gene expression and linked this to survival outcome using RNAseq data from cervical tumor samples published by The Cancer Genome Atlas (TCGA)." (PMID 30050535, 2018). "Rather, a marginal IDO expression pattern in the tumor dominantly predicts favorable outcome, which might be related to IFNγ release in the cervical tumor microenvironment." (PMID 30050535, 2018). "In addition, we compared the relationships between IDO1 and IFNG gene expression and clinical parameters using RNAseq data from 144 cervical tumor samples published by The Cancer Genome Atlas (TCGA)." (PMID 30050535, 2018). "Indeed, TCGA analysis of 144 cervical tumor samples revealed a strong and positive correlation between IDO1 and IFNG mRNA expression levels (P < 0.001) and a significant association with improved DFS for high IDO1 and IFNG transcript levels (P = 0.031)." (PMID 30050535, 2018). "The cervical tumor microenvironment is rich in pro-inflammatory cytokines such as interleukin-6 (IL-6), tumor necrosis factor-alpha (TNF-α), and interferon-gamma (IFN-γ), which interfere with iron metabolism and erythropoiesis." (PMID 40901092, 2025). "Tumor sections from a group of 58 patients with deep normal tissue-invading cervical tumors were stained for the presence of immune cells (CD45), IFNγ-producing cells (Tbet) and regulatory T cells (Foxp3) by immunohistochemistry." (PMID 26357849, 2015).
gastric adenocarcinoma (9 papers, 2011 to 2025). "This, along with enriched neighborhood genes for IL2, interferon gamma (IFNG), and IL12, augment the argument that innate responses may play a significant role in the immune microenvironment of gastric SRCC compared to gastric adenocarcinoma." (PMID 41511314, 2025).
Helicobacter infection (9 papers, 2009 to 2024). "Helicobacter infection is strongly associated with the induction of a strong Th1-type inflammatory response, with high levels of Ifnγ, which induces expression of other inflammatory mediators such as iNOS and Cox-2, and also circulating growth factors such as gastrin." (PMID 19317916, 2009). "The analysis of the most prominent pro-inflammatory cytokines involved in Helicobacter infection (IL8, IL6, TNFα, IL1β and IFNγ) revealed that the main difference between the two conditioned media was on IFNγ, not expressed in the THP1 system." (PMID 36514982, 2022).
hypertriglyceridemia (9 papers, 2013 to 2025). A laboratory test result indicating elevated triglyceride concentration in the blood. "IL-1 mediates fever, hyperferritimia, coagulopathy, and production of IL-18; IL-18 likely mediates hypersplenism, hypertriglyceridemia, hypotension, and elevated IFNγ." (PMID 30459597, 2018). "In patients with MAS, free IL-18 significantly correlated with clinical status and biologic markers of MAS, such as anemia, hypertriglyceridemia, and hyperferritinemia, but also with markers of Th1 lymphocyte or macrophage activation, such as IFNγ and soluble receptors for IL-2 and TNFα." (PMID 30459597, 2018).
kidney cancer (9 papers, 2007 to 2022). Primary or metastatic malignant neoplasm involving the kidney. "However, high expression of cytolytic markers, GZMA or IFNG tend to suggest a good prognosis in blood and kidney cancers, respectively." (PMID 35197510, 2022). "Why higher expression of the immunomodulator IFNγ is associated with cancer virulence for this type of kidney cancer is not clear." (PMID 26384298, 2015).
kidney tumor (9 papers, 2007 to 2025). "Recently, Godin-Ethier reported that activated T cells induce functional IDO expression in breast and kidney tumor cell lines and that this was partly attributable to IFNγ." (PMID 22013481, 2011).
lung squamous cell carcinoma (9 papers, 2016 to 2024). "In lung squamous cell carcinoma, the low YTHDF1 group was also mainly enriched in immunity-related signaling pathways (allograft rejection, IL2-STAT5 signaling, inflammatory response, IL6-JAK-STAT3 signaling, and TNFA signaling via NFKB and interferon gamma response)." (PMID 36479088, 2022).
memory impairment (9 papers, 2014 to 2025). "To further strengthen our hypothesis that early IFNγ exposure drives later memory impairment we injected female mice directly with IFNγ during early postnatal stage and found memory impairment in both behavioral tasks when mice had reached adolescence." (PMID 37169749, 2023).
oral squamous cell carcinoma (9 papers, 2019 to 2025). "AhR also plays a central role in IFNγ-induced expression of IDO1, PD-L1, CTLA-4, LAG-3, and CD39 in an oral squamous cell carcinoma model." (PMID 38632994, 2024).
papilloma (9 papers, 2011 to 2024). A benign epithelial neoplasm that projects above the surrounding epithelial surface and consists of villous or arborescent outgrowths of fibrovascular stroma. "Further, CD8+ T cell activation to produce IFNγ for the splenocytes taken from unvaccinated C57BL/6 mice that had spontaneously cleared papilloma detected a T cell response only to mE6 90–99." (PMID 26495972, 2015). "We also confirmed upregulated expression of IFNγ-related genes by RT-qPCR, including IFNγ, PD-L1, CXCL9 and CXCL10 in K17KO papillomas." (PMID 31968015, 2020). "Since many of the most significantly upregulated pathways in K17KO papillomas were associated with immune responses, we measured infiltrating immune populations by flow cytometry as well as IFN gamma (IFNγ)-related gene expression levels by RT-qPCR in K17KO and WT papillomas." (PMID 31968015, 2020).
Pruritus (9 papers, 2012 to 2025). Pruritus is an itch or a sensation that makes a person want to scratch. "The inhibition of JAK ensures the inhibition of receptors; therefore, the subsequent biological effects, from a greater number of cytokines, are variably involved in the pathogenesis of pruritus, not only IL13 and IL4 but also IL31, IL2, IL8, IL25, IL33, IFNγ and thymic stromal lymphoprotein (TSLP)." (PMID 35890180, 2022).
upper respiratory tract infection (9 papers, 2015 to 2025). "Moreover, IL-2, IL-4, and interferon-gamma (IFN-γ) levels that rise during upper respiratory tract infections are reduced after spa inhalation treatment, while anti-inflammatory cytokines, such as IL-10, are increased." (PMID 39452476, 2024). "reduce IFNγ & TNF-α and increase IL-4 & IL-10 secretions to control the immunostimulatory effects in upper respiratory tract infection." (PMID 39294611, 2024).
Anorexia (8 papers, 2012 to 2025). Lack of desire to eat (loss of appetite). "Previous studies have shown that injection of ASP, GM-CSF, and IFNγ within the cerebral ventricles resulted in anorexia." (PMID 26734008, 2015). "TNFα and IFNγ have been shown to play an important role in LPS-induced anorexia." (PMID 26734008, 2015). "Furthermore, inflammatory mediators, such as interferon-gamma (IFN-γ), interleukin-6 (IL-6) and tumor necrosis factor-alpha (TNF-α) may contribute to anorexia, adipose tissue loss and muscle atrophy." (PMID 22761662, 2012). "Cachexia often appears with anorexia as a result of imbalances between pro-inflammatory (e.g., TNF-α, IL-1, IL-6, interferon-gamma [IFN-γ]) and anti-inflammatory cytokines (e.g., interleukin-4 [IL-4], interleukin-12 [IL-12], interleukin-15 [IL-15])." (PMID 28177923, 2017).
biliary atresia (8 papers, 2006 to 2022). A rare, biliary tract disease characterized by progressive obliterative cholangiopathy of the intra- and extrahepatic bile ducts, occurring in the embryonic/ perinatal period, leading to severe and persistent neonatal jaundice and acholic stool. "Here, we show that such an increase is not essential for the expression of the proinflammatory response in experimental biliary atresia, as demonstrated by the increases in mRNA levels for IFNγ, and TNFα at the onset of jaundice and acholic stools in mice lacking IL-12." (PMID 16623951, 2006). "To directly investigate whether IFNγ played a key role in pathogenesis of biliary injury, we first determined the functional commitment of lymphocytes in the hepatobiliary system in a mouse model of rotavirus-induced biliary atresia." (PMID 16623951, 2006). "Pro-inflammatory Th1 cytokines, such as tumor necrosis factor-alpha (TNF-α) and interferon-gamma (IFN-γ), are induced in primary sclerosing cholangitis, PSC, and biliary atresia." (PMID 32846954, 2020). "Livers of infants with biliary atresia and of neonatal mice infected with rotavirus (RRV) have increased expression of interferon-gamma (IFNγ) and interleukin (IL)-12." (PMID 16623951, 2006).
brain inflammation (8 papers, 2010 to 2024). "PACAP may therefore be useful in treatment of brain inflammation and to enhance recruitment of endogenous NPCs after injury and conditions with high IFNγ production." (PMID 20559421, 2010).
Burkholderia Infections (8 papers, 2012 to 2025). Infections with bacteria of the genus BURKHOLDERIA. "Recently it has been proposed that in the early phase of Burkholderia infection caspase-11 may act as an IFNγ-inducible effector mechanism because of its reliance on the IL-18-IFNγ axis for priming, which would place non canonical inflammasome downstream of canonical caspase-1 activation." (PMID 29791511, 2018).
Candidemia (8 papers, 2013 to 2025). A form of invasive candidiasis where species of CANDIDA are present in the blood. "In addition, interferon-gamma improved the immune response in a child suffering from refractory candidemia with extremely low mHLA-DR." (PMID 34755207, 2022).
cholangitis (8 papers, 2013 to 2023). An acute or chronic inflammatory process affecting the biliary tract. "In cholangitis, miR-221 regulates the secretion of cell adhesion molecule 1 induced by interferon gamma in bile duct cells." (PMID 26901347, 2016).
chordoma (8 papers, 2015 to 2025). Chordomas are rare malignant tumors arising from embryonic remnants of the notochord in axial skeleton. "Preclinical evidence for the use of PD-L1 inhibitors suggests that chordoma cells express PD-L1, expression of which is further inducible by interferon gamma, and that chordoma CSCs are sensitive to PD-L1 inhibitor-mediated ADCC." (PMID 38741774, 2024). "We have previously reported that exposure of chordoma cells to IFNγ increases PD-L1 expression on the cell surface, augmenting anti–PD-L1 antibody-mediated ADCC." (PMID 35765577, 2021). "Our study showed that IFNγ increased PD-L1 expression (both % positive cells and MFI) on 2 of 2 chordoma cell lines and in turn, enhanced the susceptibility of these cell lines to lysis by PD-L1 t-haNK cells (P ≤ 0.0001)." (PMID 35765577, 2021). "Here, we hypothesized that treatment of chordoma cell lines with IFNγ would upregulate PD-L1 expression, thus increasing their sensitivity to lysis by PD-L1 t-haNK cells." (PMID 35765577, 2021).
demyelination (8 papers, 2015 to 2025). "Though it should be noted that others have noted immune cell infiltration and IFNg production in cuprizone-induced demyelination." (PMID 36261842, 2022). "CD8+ CTLs in the CNS produce and release several pro-inflammatory cytokines including interferon-γ (IFNγ) and tumor necrosis factor-α (TNF-α), which is proposed to result in substantial bystander destruction of resident CNS tissue and neural cells associated with demyelination." (PMID 37622115, 2023). "In these studies, we used the EAE model, as well as the cuprizone-induced demyelination model on GFAP-tTA;TRE-IFN-γ double-transgenic mice, which ectopically express interferon gamma (IFN-γ) in the CNS in a regulated manner." (PMID 33752802, 2021).
herpesvirus infection (8 papers, 2013 to 2025). "It has been reported that interferon gamma production is increased during herpesvirus infection or VZV vaccination, resulting in activation of cellular immunity." (PMID 36181532, 2023). "The intricacies involving the role of interferon-gamma (IFN-γ) in herpesvirus infection and persistence are complex." (PMID 24567732, 2014). "In human recurrent herpes infections, both CD4+ and CD8+ TRM persisting between lesions may control asymptomatic shedding through interferon-gamma secretion, although this has been more clearly shown for CD8+ T cells." (PMID 33668777, 2021).
Hodgkins lymphoma (8 papers, 2004 to 2024). A heterogeneous group of malignant lymphoid neoplasms of B-cell origin characterized histologically by the presence of Hodgkin and Reed-Sternberg (HRS) cells in the vast majority of cases. "We present a case of cervical lymphadenopathy in a child with positive purified protein derivative (PPD) and Interferon-Gamma Release Assay results, ultimately diagnosed with Hodgkin's lymphoma via cervical lymph node biopsy." (PMID 39421032, 2024).
Hypoglycemia (8 papers, 2013 to 2025). A decreased concentration of glucose in the blood. "However, hypoglycemia markedly reduced the expression of interferon-gamma (IFNγ) and, to a lesser degree, tumour necrosis factor-alpha (TNFα), key indicators of effector function, while interleukin-2 (IL-2) production was unaffected." (PMID 40575013, 2025). "Both IL-2 and IFNγ are also critical in Dgal-sensitized models of superantigen-induced shock as IL-2 deficient mice were resistant to SEB-induced shock and antibodies to IFNγ inhibited SEB-induced weight loss and hypoglycemia." (PMID 24064719, 2013).
infarction (8 papers, 2019 to 2025). A localised pathological necrosis of tissue resulting from obstruction of the blood supply usually by a thrombus, an embolus, or vascular torsion. "In our analysis, serum Troponin I levels at 7 days post-infarction showed a positive correlation with CD4 + IFNγ+ lymphocytes, suggesting that patients with a high percentage of CD4 + IFNγ+ lymphocytes at 1 h post-infarction may have higher circulating Troponin I levels at 7 days." (PMID 30898123, 2019). "The analysis showed a strong positive correlation between the percentage of CD4+ IFNγ+ T cells 1 h after AMI and the levels of Troponin I at 7 days post-infarction (r = 0.7847; p = 0.0367)." (PMID 30898123, 2019).
joint disease (8 papers, 2012 to 2023). "We previously showed that aged Dcir−/− mice spontaneously developed joint ankylosis, and that this and other bone abnormalities were due to an increased number of IFNγ-producing T cells." (PMID 37266426, 2023). "We found that elevated IFNγ production, induced by prior acute Plasmodium infection, exerts an anti-viral effect, abrogating systemic viral load and suppressing early virus replication in the joint tissue, leading to abolished joint disease." (PMID 30254309, 2018). "Therefore, the increased proportion of cells making IL-22 alone (that is, without IL-17 or IFNγ) in Ps skin compared to joints was of particular interest, given that this has not previously been studied in patients with both skin and joint disease." (PMID 24286492, 2013).
malignant glioma (8 papers, 2014 to 2023). A grade III or grade IV glioma arising from the central nervous system. "We however observed that exposure of peripheral blood of patients with malignant glioma to CMV-pp65 antigen in the absence of cytokine conditioning did not enhance significantly the IFNγ production." (PMID 29970101, 2018).
metastatic carcinoma (8 papers, 2014 to 2023). A carcinoma which has spread from the original site of growth to another anatomic site. "In metastatic cancer, these pathways are activated by pro-inflammatory cytokines such as interleukin 6 (IL-6), interleukin 1 (IL-1), tumor necrosis factor alpha (TNF-α), and interferon gamma (IFN-γ)." (PMID 35994202, 2022).
osteomyelitis (8 papers, 2010 to 2025). An acute or chronic inflammation of the bone and its structures due to infection with pyogenic bacteria. "When TB osteomyelitis is suspected, a history of TB or exposure and an interferon-gamma release assay can help to confirm the diagnosis before surgery." (PMID 32831075, 2020).
Rickettsiosis (8 papers, 2015 to 2025). A group of infectious diseases that is caused by Rickettsia. "Mice lacking IFNγ (IFNγ-/-) or its receptor (IFNGR-/-) often demonstrate enhanced susceptibility to rickettsiosis." (PMID 38567021, 2024). "Antigens that elicit strong cellular responses, including IFNγ secreting CD4+ and CD8+ T cells, are likely necessary for protection against rickettsial diseases." (PMID 38567021, 2024). "Elevation of serum IFNγ and IL-15 concentrations were also noted in R. parkeri-inoculated animals at 1 and 4 dpi indicating evidence of a TH1 response in these animals, which has been well described in SFG rickettsiosis." (PMID 26244337, 2015).
Shock (8 papers, 2012 to 2025). The state in which profound and widespread reduction of effective tissue perfusion leads first to reversible, and then if prolonged, to irreversible cellular injury. "Patients with septic shock present higher IL-6 and IL-8 plasma levels and lower levels of IFNγ than patients with infection, showing that an impaired immune response contributes to a worse prognosis." (PMID 36536294, 2022). "The cytokines, interleukin 1 (IL-1), tumor necrosis factor α (TNFα), and interferon gamma (IFNγ) are pivotal mediators in animal models of superantigen-induced toxic shock." (PMID 25688664, 2015).
sialadenitis (8 papers, 2007 to 2025). Sialadenitis is an infection of the salivary glands. "These cells produce IL-1β, IFNγ, and TGFβ, which activates fibroblasts and alternatively activated (M2) macrophages, thereby inducing fibrosis in IgG4-related dacryoadenitis and sialadenitis." (PMID 34391459, 2021). "A study conducted by Cha and colleagues illustrated an important role for Ifnγ in exocrinopathy, in which neither the NOD Ifnγ null nor the NOD IfnγR (encoding interferon-γ receptor) null mice developed sialadenitis or secretory dysfunction, like their NOD littermates did." (PMID 17900348, 2007).
synovitis (8 papers, 2010 to 2025). Inflammation of a synovial membrane. "Our demonstration that the local presence of IL-17 producing CD4+ T cells (either Th17 or IL-17+IFNγ+ T cells) in the RA joint is associated with active synovitis measured by PDUS, provides novel mechanistic insight into PDUS-related immunopathology." (PMID 20824142, 2010).
Achalasia (7 papers, 2015 to 2025). A disorder of esophageal motility characterized by the inability of the lower esophageal sphincter to relax during swallowing and by inadequate or lacking peristalsis in the lower half of the body of the esophagus. "We also found many pro-inflammatory factors in expanded effector T cells and effector memory T cells that were more highly expressed in achalasia than in controls, including TNF, IFNG, GZMB, and GZMH." (PMID 37542039, 2023). "Patients with achalasia are characterized by significantly higher esophageal lymphocyte infiltration, mainly represented by CD3+CD8+ T cells and IL-1β, IFNγ, and IL-232." (PMID 27511445, 2016).
adenomyosis (7 papers, 2017 to 2025). The growth of endometrial tissue inside the muscular wall of the uterine corpus. "Ectopic mononuclear cells of women with adenomyosis produced higher levels of IFNγ, IFNα and TNFα than the mononuclear cells of eutopic endometrium." (PMID 29178922, 2017). "In external adenomyosis, the analysis predicted the activation of multiple upstream regulators such as LPS, TGFB1, IL4, and IFNG." (PMID 40531845, 2025).
Airway obstruction (7 papers, 2005 to 2025). Obstruction of conducting airways of the lung. "However, it is unclear, based on our current understanding of macrophage functional heterogeneity, if immature AM improve viral clearance or contribute to inflammation and airway obstruction in the IFNγ-deficient neonatal lung environment." (PMID 22792355, 2012). "Neutrophil infiltration has been implicated as a contributing factor in airway obstruction in severe RSV disease, thus some caution is warranted for consideration of IFNγ as a vaccine or therapeutic tool in infant RSV disease." (PMID 22792355, 2012).